CDY1B (chromodomain Y-linked 1B)
Description:
Has histone acetyltransferase activity, with a preference for histone H4.
Synonyms: CDY
Target class: Epigenetic regulator; Reader; Methyl-lysine/arginine binding protein; Chromodomain
Gene: Protein-coding gene on chromosome Y (24,045,229 to 24,048,019, reverse strand). Ensembl gene ENSG00000172352.
Subcellular location: Nucleus
Gene Ontology:
Molecular function: histone H3K27me3 reader activity; histone H3K9me2/3 reader activity; transcription corepressor activity; protein-lysine-acetyltransferase activity
Biological process: negative regulation of peptidyl-lysine crotonylation; spermatogenesis; chromatin organization; negative regulation of DNA-templated transcription
Cellular component: nucleus
Homologues: Orthologues: macaque CDY (83% identical), mouse Cdyl (61% identical), zebrafish cdyl (47% identical), rat AABR07039112.1 (41% identical), Caenorhabditis elegans B0272.4 (13% identical), Drosophila melanogaster Dci (12% identical), Drosophila melanogaster CG8778 (10% identical), Caenorhabditis elegans ech-5 (10% identical), Drosophila melanogaster Srlp (10% identical), Drosophila melanogaster CG14787 (9% identical), Drosophila melanogaster HIPP1 (9% identical), Caenorhabditis elegans ech-3 (9% identical), and 1 more. Paralogues in human: CDY1 (99% identical), CDY2A (98% identical), CDY2B (98% identical), CDYL (63% identical), CDYL2 (38% identical), ECHS1 (14% identical), ECHDC2 (12% identical), ECHDC3 (12% identical), HIBCH (12% identical), ECH1 (11% identical), AUH (11% identical), ECI1 (10% identical), and 1 more.
Diseases named in the same sentence as CDY1B in open-access papers:
CDY1B is named in the same sentence as 2 diseases in open-access papers, as found by Europe PMC text mining. Sharing a sentence is not in itself a finding about the gene and the disease. The quoted sentences say what the papers report.
male infertility (3 papers, 2019 to 2025). The inability of the male to effect fertilization of an ovum after a specified period of unprotected intercourse. "A strong association exists between loss of the CDY1a sequence family variant and male infertility (p = 0.002); overall, this genetic alteration, due to gene deletion or conversion, may represent a major risk factor for male infertility; a similar scenario has been described for CDY1b." (PMID 31905733, 2019).
Azoospermia (2 papers, 2016 to 2018). Absence of any measurable level of sperm,whereby spermatozoa cannot be observed even after centrifugation of the semen pellet. "In a similar study concomitant deletion of both DAZ and CDY1 copies in males predisposes them to azoospermia or severe oligozoospermia deletion of CDY1b copy alone is also reported to be associated with oligo/azoospermia." (PMID 29454353, 2018).